CD4 (CD4 molecule)
Diseases named in the same sentence as CD4 in open-access papers (continued):
Sharing a sentence is not in itself a finding about the gene and the disease.
diabetes (continued). "Those parameters could be improved by better training of local staff, highlighting that finger stick for quantitative CD4 enumeration is not similar to finger stick blood for a thick smear (malaria) or for blood sugar measurements (diabetes)." (PMID 27556894, 2016). "Third, our findings could also be cofounded by co-morbidities such as smoking status, diabetes, adherence to the prescribed medicines or baseline CD4 versus CD4 counts at six months, which we did not analyse as these data were not collected." (PMID 27303572, 2016). "As IC87114 did not have an effect on development of diabetes after transfer of BDC2.5 cells we wished to elucidate whether it could decrease IFN-γ production from already Th1 differentiated effector CD4+ T cells." (PMID 26783747, 2016). "Indeed, it has been demonstrated that β-islet cell self-reactive CD4+ T cells were not sufficient, and IL-7-mediated homeostatic proliferation was necessary to induce overt diabetes mellitus." (PMID 24586733, 2014). "The characteristic features of untreated diabetes progression in NOD mice are the increased infiltration of CD8+ cytotoxic T cells into the islets and pancreatic lymph nodes (PLNs) together with a concomitant decrease in the frequency and activity of CD4+CD25+Foxp3+ Tregs in the same compartments." (PMID 25259810, 2014). "Consequently, negative coefficients of CRP, diabetes, and fatty liver on TRECs were observed in both CD4 and CD8 T cells." (PMID 24651652, 2014). "However, data on this particular T-cell subset and its implication in diabetes are still lacking; particularly, there are no studies exploring the role of CD4+CD28null T-cells in T1DM and its complications." (PMID 23762872, 2013). "It is still unclear though, whether the increased expression of CD4 + Vβ4 in newly diagnosed T1DM children of Hellenic origin is a constant finding in later stages of diabetes or not." (PMID 23915345, 2013). "This study purports to investigate the relationship of ethnicity and CD4+ T cell count attained after stable highly-active antiretroviral treatment (HAART) with glucose metabolism in hyperrtriglyceridemic HIV patients without a history of diabetes." (PMID 23607267, 2013). "Thus, reduced overall thymyocyte numbers, combined with maintenance of CD4 SP cells, might contribute to the RRV-mediated diabetes delay." (PMID 23554993, 2013). "The delayed onset of diabetes relied on a shift from a Th1 to a Th2 profile in pancreatic lymph nodes and an increase in TGF-β in the mesenteric lymph nodes (MLN) and the induction of antigen-specific CD4+ Treg in the area of the mucosal barrier and inflamed islets." (PMID 23970886, 2013). "Since laboratory capabilities differed by country and study site, some of the studies did not adjust for baseline CD4 count, body mass index, smoking, and/or diabetes, which could confound results." (PMID 22911011, 2012). "Unlike unfractionated CD4+ pancreatic LN cells from Non-Sick CFA-treated NOD mice, CD25+-depleted CD4+ cells from the same population were unable to protect against diabetes and, in fact, transfer of these cells increased the incidence of disease (to 100%) by comparison to untreated controls." (PMID 19011680, 2008). "Also in the NOD mice, the induction of CD4+ NKT cells was only observed in the draining pancreatic lymph node, and the missing systemic effect was confirmed by adoptive transfer of splenocytes from B. fragilis‐treated NOD mice that was unable to transfer protection against diabetes." (PMID 39136533, 2024). "It was concluded that a lower nadir cluster of differentiation 4 (CD4) T cell count nadir was independently associated with worse endothelial function in HIV-infected patients, despite effectively suppressed viral load and without hypertension, diabetes, or clinical evidence of CVD." (PMID 36909130, 2023).
diabetes (continued). "The condition could be a consequence of a dysregulated immune system due to a reduction in T cell count, altered CD4/CD8 ratio, and overuse of immunosuppresses like corticosteroids following the COVID‐19 which is exacerbated by uncontrolled blood sugar in people with undetermined diabetes cases." (PMID 36276900, 2022). "While the significant reduction of insulin-specific CD4+ and CD8+ T cells in TIP-1 is suggestive of deletional tolerance, it is possible that transgenic antigen expression in APCs may induce regulatory T cells (Tregs) that confer dominant tolerance and prevent diabetes in TIP-1 mice." (PMID 33841427, 2021). "Since a higher number of CD4+ cells and a lower number of CD8+ cells were present in the islets of DNA-HSP65-injected and DNAv-injected mice in relation to STZ group, we supposed that CD4+ cells with a regulatory phenotype could be involved in down modulation of diabetes development." (PMID 19754943, 2009). "Participants with T1D, but not with T2D, showed a significant decrease in the frequency of S‐specific CD4+ T cells, identified as CD154+CD69+, compared with people without diabetes (approximately 2.7‐fold decrease in T1D compared with the no diabetes group)." (PMID 41367201, 2025). "In mouse studies, the proportion of CD4+ and CD8+ T cells in the liver was not affected by diabetes; however, the activated CD4+(CD69+) and CD8+(CD69+) T cell counts were higher in diabetes (FC = 2.5 and 2, respectively, both p < 0.05) vs. non-diabetes." (PMID 40362271, 2025). "We found defects in both CD4+ and CD8+ T cell memory maintenance and the functionality of the vaccine‐specific T cells in people with diabetes compared with people without." (PMID 41367201, 2025). "It is well established that, in human subjects with T1D and non-obese spontaneous diabetes-prone (NOD) mice, both CD4+ and CD8+ T cells are major components of the islet infiltrate and critical contributors to T1D development." (PMID 39359722, 2024). "Both CGC+ CD4+ and CGC+CD8+ T cells were significantly higher among participants with prediabetes and diabetes as compared to non-diabetics." (PMID 36865544, 2023). "Diabetes and prediabetes were not significantly different by HIV‐related factors, including CD4 count and ART." (PMID 36924213, 2023). "Thus, it is reasonable to conclude that the increase of PD-1+CXCR5+CD4+ Tfh cells in peripheral blood from DR patients could reflect GCs dysregulation and aberrant immune responses in the lymphoid and non-lymphoid tissues during diabetes." (PMID 32226551, 2020). "Overall, these data indicate that, compared with PB, VAT-derived CD4 and CD8 T cells display hyper-responsiveness in patients with obesity regardless of the presence of diabetes." (PMID 32299896, 2020). "While vaccination with the combination therapy increases CD4+CD49b+LAG3+ Tr1 cells, it was not clear if these cells carried specificity to a diabetes relevant antigen." (PMID 30863412, 2019). "Neutralization of circulating IL-2 elicits autoimmune gastritis in BALB/c mice and triggers early onset of diabetes by inhibiting physiological proliferation of peripheral CD4+CD25+ cells, but not CD4+CD25− cells." (PMID 29725328, 2018). "The proportion of CD4+ T cells was increased and that of CD8+ T cells was reduced after glucose loading in both subjects with and without diabetes." (PMID 29615971, 2018). "Independent of inhibiting the recruitment of activated CD4 + and CD8 + T cells to islets, B7-H4 Ig treatment significantly postponed the disease onset and reduced incidence of diabetes in NOD mice due to a transient increase of Treg cells population." (PMID 29416823, 2018). "We found that the proportion of CD4+ T cells increased and that of CD8+ T cells decreased after glucose loading in subjects with and those without diabetes." (PMID 29615971, 2018). "While the majority of insulin-specific CD4 T cells in NOD mice are anergic, this form of tolerance is not sufficient o halt diabetes." (PMID 29259578, 2017).
diabetes (continued). "Together, these observations suggest that reduction in IFN-γ and TNF-α expressing pro-diabetogenic CD4+ and CD8+ T cells, without any enhanced contribution from Treg cells, likely accounts for attenuation of diabetes in pCD11c-Aire mice." (PMID 28966617, 2017). "By contrast, ICOSL−/− CD8+ T-cells alone or splenocytes depleted in CD4+ T-cells and CD8+ T-cells (CD4−CD8− T-cells) did transfer neither neuromyopathy nor diabetes." (PMID 28424681, 2017). "In a model of T1D induced by transfer of NOD-BDC2.5+ CD4+ T cells into NOD-scid recipients, diabetes developed rapidly approximately 10 days later without any intervention (black line)." (PMID 25998054, 2015). "Percentages of CD3+CD4+CD8- splenocytes expressing IFN-γ after stimulation with PMA and ionomycin were not affected by diabetes or NFAT inhibition." (PMID 23755169, 2014). "Although CD4 T cells are crucial to diabetes progression, mice that lack CD8 T cells develop neither insulitis nor diabetes, suggesting that CD8 T cells participate in β cell destruction." (PMID 23671851, 2013). "Other factors including ethnicity, b-blocker, anti-hyperglycaemic medications, diabetes mellitus, FPG, CD4, smoking and alcohol consumption did not result in high level of TC significantly (p > 0.05)." (PMID 23947428, 2013). "First, due to the absence of naturally occurring CD4+CD25+ Tregs, these mice exhibited accelerated disease development compared to wild-type NOD mice (overt diabetes is usually observed by 8 weeks of age)." (PMID 19936238, 2009). "While TNFR1-dependent islet responsiveness has been shown to be critical for islet destruction by CD4 T cells, islet TNFR2 responses were not required for this CD4-mediated diabetes." (PMID 17254331, 2007). "Independent predictors of diabetes included older age (adjusted odds ratio (AOR) = 1.14; 95% confidence interval (CI) = 1.05-1.25; p = 0.003), absence of a family history of diabetes (AOR = 0.07; 95% CI = 0.02-0.27; p < 0.001), and CD4 count <200 cells/μL (AOR = 0.14; 95% CI = 0.02-0.88; p = 0.036)." (PMID 41399597, 2025). "Furthermore, higher CD4 and CD8 cell counts have been observed in TB patients with diabetes compared to those with non-tuberculous pneumonia and healthy controls." (PMID 40895633, 2025). "For example, CD4+ T cell clones can transfer diabetes; on the other hand, non-obese diabetic (NOD) mice lacking MHC class I molecules develop neither insulitis nor diabetes." (PMID 39600694, 2024). "Of interest, diabetes progress in TNFα-transgenic NOD mice is CD8+, but not CD4+, T cell dependent." (PMID 34778464, 2021). "Injection of non-depleting anti-CD4 antibody YTS177 can suppress adaptive immune responses and induce immunological tolerance to islet antigens and AAV capsid, but if administered alone cannot reverse overt spontaneous diabetes in NOD mice." (PMID 30514969, 2019). "However, in the absence of Tregs, IL-2 produced by infiltrating CD4+ helper T cells activated NK cells and enhanced their IFN-γ production which leads to the onset of diabetes." (PMID 26220086, 2015). "Moreover, CD4+CD25+ cells from pancreatic LN of CFA-treated, but not untreated, NOD mice transferred protection from diabetes." (PMID 19011680, 2008). "Moreover, in individuals with Type 1 diabetes mellitus (T1DM) who experience pain compared to those without, there is a proportional increase in CD4 + central memory T cells and an absolute increase in classical and nonclassical monocytes among peripheral blood immunophenotypes." (PMID 39075499, 2024). "However, we did not observe an increase in CD57 expression on either CD4+ or CD8+ memory cell subsets with progressive glucose intolerance, with the exception of higher CD57 expression on CD4+ TCM in diabetic individuals compared to those without diabetes." (PMID 30941121, 2019).
diabetes (continued). "This discrepancy between in vivo and ex vivo data appears not to result from the transfer of fewer p509 or p530-expanded CD4+CD25+ T cells compared to those expanded by p524, as even a 3–5 fold increase (e.g. 3−5×106) in p509 or p530-expanded CD4+CD25+ T cells failed to inhibit transfer of diabetes." (PMID 19759824, 2009). "Furthermore, in EA16 mice, which do not develop diabetes because the transgenic expression of an I-E molecule confers almost complete protection from insulitis of NOD mice, the percentage of CD4 T cells in the bone marrow was significantly increased as compared to Balb/c mice." (PMID 18793419, 2008). "Also CD4+CD28− T cells occur in diabetes mellitus, with higher levels in case of the first cardiovascular event and acute coronary syndrome compared to diabetes mellitus patients without a cardiovascular syndrome and patients with acute coronary syndrome but without diabetes mellitus." (PMID 25834833, 2015).
asthma (674 papers, 1995 to 2026). "ROC curve analysis demonstrated that CD4+PD-1+LAG-3+ T cells had superior diagnostic performance for moderate-to-severe asthma." (PMID 41737415, 2026). "In our study, we observed significant mediation effects where 1‐myristoyl‐2‐arachidonoyl‐GPC (14:0/20:4) levels mediated a substantial proportion of the effect of CD3 on CD28+ CD4+ T cells on asthma risk." (PMID 40551049, 2025). "From this regression model, the representative variables (RVs) for CD8 cluster 2 (3.71 [1.06–13.04]), ILC/NK cluster 7 (5.71 [1.15–28.34]), and CD4 cluster 14 (3.06 [1.02–9.22]) were positively associated with non‐T2 asthma when compared to non‐T2 controls." (PMID 40965120, 2025). "Cell populations typically associated with T2‐inflammation, namely ILC2s and CD4+ Th2 cells, were found to distinguish T2 asthma from non‐T2 asthma, supporting previous evidence that these cells contribute to this endotype." (PMID 40965120, 2025). "This substance can induce long-term immune effects, leading to CD4+ T cell dysfunction, thereby increasing susceptibility to asthma." (PMID 40861492, 2025). "The presence of CD4 or CD8 cells in bronchial wall biopsies of asthma patients has been linked to a longitudinal loss of lung function measured via spirometry." (PMID 39980176, 2025). "The increased number of DCs and CD4 + T cells in the lungs of Sema3E-deficient mice in the type-2 low asthma model, compared to WT mice, highlights the broader impact of this axis on immune regulation beyond granulocytes." (PMID 40512736, 2025). "Increased CRTH2+ CD4+ T cells, also called Th2 cells, associated with T2 features in both asthma and control subjects in our study, have previously been associated with asthma severity." (PMID 40965120, 2025). "With the most suitable MR methods, we observed that two kinds of immune-related cells had protective causal effects on asthma (CD4+ T: OR = 0.78, p = 1.73 × 10–13; CD4+ T/CD8+ T: OR = 0.92, p = 2.42 × 10–02)." (PMID 38263182, 2024). "Dysregulation of CD4 T lymphocytes (Th1, Th2, Th17, and Teg) is believed to be linked to the pathophysiology of MG and asthma." (PMID 39544556, 2024). "Th17 cells, a subset of CD4+ T‐cells, are associated with a more severe asthma phenotype, and IL‐17 can increase NF‐κB activation and secretion of neutrophil chemokines." (PMID 38488697, 2024). "The results showed that the proportion of CD4+CD44+ T cells, especially CD4+ TRMs, is positively correlated with the severity of asthma symptoms caused by RSV infection, as well as several other molecular markers." (PMID 39632661, 2024). "Several factors are reported to be linked with the pathogenesis of asthma, such as dysregulation of the immune response driven by cluster of differentiation 4+ (CD4+) T helper (Th) cells, airway inflammation, airway hyperresponsiveness, and airway remodeling." (PMID 37644509, 2023). "Th2 cells are the main T cells associated with pathogenesis in asthma; however, in allergic asthmatics, they remain low in number, even among allergen-specific CD4 T cells." (PMID 37163370, 2023). "Naive CD4+ T cells differentiate into functionally diverse Th cell subsets, and Th2 cells play a pathogenic role in asthma." (PMID 38203236, 2023). "We also found increased concentration of IL-16, a cytokine linked to inflammatory processes, such as in asthma, in which its levels correlated with the number of infiltrating CD4+ cells." (PMID 37006253, 2023). "We previously reported that our chronic asthma model was associated with heightened numbers of CD4 T cells and CD4+ nTregs, and that CD4 T cells contributed to the increased magnitude of airway inflammation." (PMID 37575259, 2023). "They found that MEG3 expression levels were upregulated and negatively associated with miRNA-17 expression in CD4+ T cells of patients with severe asthma." (PMID 35769905, 2022).